MMP9 (matrix metallopeptidase 9)
Diseases named in the same sentence as MMP9 in open-access papers (continued):
Sharing a sentence is not in itself a finding about the gene and the disease.
dry eye (continued). "In addition, matrix metalloproteinase-9 (MMP-9), a gelatinase produced in the corneal epithelium and activated in the tear film, is currently used as a marker for the diagnosis of dry eye." (PMID 35886858, 2022). "Therefore, supplemental measurements that evaluate inflammation, such as MMP-9 and tear film osmolarity, can help to diagnose dry eye in clinical practice." (PMID 35450324, 2022). "Thus, while MMP-9 is considered as a classic dry eye marker and clinical tests are commercially available, its usefulness as a biomarker after refractive surgery is difficult to evaluate due to a wide variability in levels in some patients." (PMID 35886858, 2022). "–5 Among these, the levels of MMP-9 in the dry eye have been shown to correlate strongly with the severity of DED and may be decreased by adequate treatment." (PMID 36201200, 2022). "Overall, our findings suggest that MMP-9 and tear film osmolarity evaluations may be used to easily and conveniently identify inflammation in patients with dry eye." (PMID 35450324, 2022). "MMP-9 is an inflammatory marker that is increased in the tears of patients with dry eyes." (PMID 35450324, 2022). "Additionally, two commercially available objective dry eye tests, including tear film matrix metalloproteinase-9 (MMP-9) and tear film osmolarity, can also be used to diagnose dry eye." (PMID 35450324, 2022). "Therefore, commercially available MMP-9 and osmolarity tests have been introduced to facilitate the diagnosis of dry eye in the clinic." (PMID 35450324, 2022). "However, in the rabbit with induced dry eye, the treatment with Artemia salina decreased the mRNA expression of MMP9 in comparison with the HPMC (p = 0.021)." (PMID 34769429, 2021). "IL-17A may be related to inflammation in dacryoadenitis and in the salivary glands, while MMP-9 may be involved in the early phase of dry-eye syndrome and tissue fibrosis." (PMID 34630072, 2021). "Previous studies have shown that mRNA expression levels of interleukin (IL)-1β, IL-6, IL-8, tumor necrosis factor (TNF)-α, interferon (IFN)-γ, and matrix metallopeptidase (MMP)-9 were significantly increased in tears and conjunctiva of dry eye patients compared to normal controls." (PMID 33921231, 2021). "An accumulation of pro-MMP-9 could clearly be observed in tear fluid from rats with dry eye treated with UAMC-00050." (PMID 33057006, 2020). "Hypothesizing that MMPs might be similarly involved in ocular surface disease, Pflugfelder and his team demonstrated elevated MMP9 levels in the tears of human patients with ocular rosacea and dry eye." (PMID 33374364, 2020). "In conclusion, this study provides some evidence that exercise may attenuate acute perceptions of dry eye symptoms and MMP‐9 in tears when exposed to a desiccating environment." (PMID 31997577, 2020). "To account for this, we included MMP‐9 as an objective biological marker of dry eye." (PMID 31997577, 2020). "Matrix metalloproteinase 9 (MMP‐9) is an endopeptidase involved in extracellular matrix remodeling and inflammation after corneal surface damage and has become a key biological marker for dry eye due to its direct relationship with dry eye severity." (PMID 31997577, 2020). "However, 20% RH appeared to increase the perception of the frequency of dry eye symptoms and presence of MMP‐9 in tears at rest." (PMID 31997577, 2020). "If InflammaDry can reflect tear concentrations of MMP-9 quantitatively, this may play a crucial role in determining the severity of inflammation and improve the outcomes for dry eye patients beyond a simple diagnosis." (PMID 32934302, 2020). "Finally, the therapeutic effect on dry eye syndrome was successfully confirmed by the Schirmer tear test, corneal fluorescein staining, and MMP9 fluorescein analysis in the DED model rabbits." (PMID 35516366, 2019). "Furthermore, the Schirmer tear test, corneal fluorescein staining, and MMP9 fluorescein analysis confirmed its therapeutic effect on dry eye syndrome in disease model rabbits." (PMID 35516366, 2019).
dry eye (continued). "Long-term dry eye is associated with increased expression of inflammatory factors, such as tumor necrosis factor-alpha (TNF-α), matrix metalloproteinase (MMP-2, MMP-9), intercellular adhesion molecule-1 (ICAM-1), and vascular cell adhesion molecule-1 (VCAM-1) in the ocular surface." (PMID 30002412, 2018). "Additionally, it has been reported that clusterin interacts with MMP-9 to reorganize the tissue by modulating ECM in corneal epithelial cells of the dry eye and in immune cells such as monocytes and macrophages in vitro." (PMID 28767729, 2017). "Elevated levels of MMP-9 have been observed in the tears of patients with dry eye." (PMID 28099212, 2017). "MMP-9 has been shown to mediate corneal barrier disruption in dry eye." (PMID 27623073, 2016). "For example, matrix metalloproteinase 9 (MMP-9) was shown to be elevated in dry eyes." (PMID 26634151, 2015). "Tear MMP9 levels have been shown to be a marker for diagnosing dry eye and ocular surface disease due to inflammation; thus, tear analysis may serve as a gauge to monitor therapy after eye surgery." (PMID 25573478, 2015). "Therefore, the increase of MMP9 activity on the ocular surface can amplify the chronic immune-based inflammation of dry eye." (PMID 26221061, 2015). "Also notable was the DHT suppression of gene expression for matrix metallopeptidase 9, an enzyme that is increased in the tear film in dry eye and is known to promote corneal inflammation." (PMID 22605918, 2012). "Expression of HO-1, COX-2, MMP-2, MMP-9, and IL-6 increased markedly in the dry eye group." (PMID 23049824, 2012). "COX-2, MMP-9, and IL-6 expression are elevated in the cornea of dry eye." (PMID 23049824, 2012). "In any case, understanding the mechanisms resulting in dry eye, inflammatory cell infiltration into the cornea, and the pattern of MMP9 expression in the corneal microenvironment will help to clarify some of the processes leading to corneal perforation in cGVHD patients." (PMID 21386923, 2011). "In addition, all 5 MMPs were efficiently recovered from these samples, including MMP-9, which has been demonstrated to be involved in corneal barrier disruption in experimental dry eye models." (PMID 21552500, 2011). "In another study in which IL-1β, IL-6, and pro-matrix metalloproteinase (MMP)-9 tear levels were measured in patients with different types of ocular diseases, including a group of 20 hyposecretive moderate dry eye patients, only proMMP9 was significantly increased in DED patients." (PMID 20508732, 2010). "More nuance in MMP-9 levels may be required, especially in low-level or mild dry eye." (PMID 40943473, 2025). "According to this immunopathogenesis of dry eye, effector immune cells such as type 17 helper T cells may cross to the contralateral corneal surface through systemic circulation to induce intermittent inflammation accompanied by MMP-9 expression in tears." (PMID 38212520, 2024). "Future studies are warranted to analyze the differences in tear film osmotic pressure and MMP-9 and to investigate whether inflammation is a predictive factor of dry eye in patients with endocrine disorders, which may help formulate treatment plans for this subgroup of patients." (PMID 37305131, 2023). "A customized AbMA test was fabricated for tear MMP-9 quantification in human samples, managing to detect the biomarker in pathologies that involve inflammation of the ocular surface, such as cataracts, glaucoma, meibomian gland dysfunction, allergy, or dry eye." (PMID 35628448, 2022). "Therefore, we think that clinicians should be very cautious about determining the gradient of MMP-9 in tear based on the density gradient of red lines in InflammaDry when they meet dry eye patients and establish therapeutic strategies using the results of InflammaDry." (PMID 34117341, 2021).
dry eye (continued). "Therefore, acute exposure of non‐dry eye sufferers to low RH conditions may provide a useful model to investigate interventions that may influence dry eye, and MMP‐9 appears to be a key objective variable of dry eye‐induced ocular surface dysfunction." (PMID 31997577, 2020). "Moreover, pro-inflammatory mediators such as matrix metalloproteinase (MMP)-9 may induce corneal stromal thinning through increased proteolytic activity at the stromal level in dry eyes." (PMID 32698387, 2020). "In addition, the potential for SDP to reduce resident MMP-9 may also suggest a role for applications in the treatment of dry eye related symptoms." (PMID 29155856, 2017). "Therefore, we postulate that 17β-estradiol may have effects on the promotion of inflammation in the lacrimal gland and conjunctival epithelium and may increase the activity of MMP-2 and MMP-9 in tears of patients with dry eye." (PMID 26904272, 2016). "Another study also showed that corticosteroid and doxycycline suppressed MMP-9, MAPK activation in the epithelium in a dry eye model." (PMID 40005905, 2025). "The results from this study demonstrate the mechanism of degradation of GelMA/PVA-based conjunctival inserts by MMP9 enzymes and its correlation with the release of PVA, a well-known wetting agent for the treatment of dry eyes." (PMID 40076115, 2025). "Other groups have illustrated that daily eye rinsing can be beneficial to reduce dry eye symptoms as illustrated with improved OSDI and dry eye questionnaire 5 in addition to reduction in MMP-9 levels." (PMID 39022763, 2024). "Given that PEDF and MMP-2 and -9 coexist in the dry eye milieus, dosing with exogenous PEDF and 29-mer to overwhelm the enzymatic activity of MMP-2 and -9 and suppress the production of MMP-9 from CECs would be beneficial for DED therapy." (PMID 36201200, 2022). "The study aimed to evaluate the correlations between tear film matrix metalloproteinase-9 (MMP-9), tear film osmolarity, and ocular surface parameters in patients with dry eyes." (PMID 35450324, 2022). "Overexpression of MMP9, MUC4, and HBD2 was observed at 24 h following the treatment with 100 μL sodium hyaluronate 0.15% (SH) of dry eye condition in comparison with the control corneal tissue (p < 0.001; Student’s t-test)." (PMID 34959420, 2021). "In cornea and conjunctiva of normal or dry eye model mice, the mRNA expression levels of IL-1β, IL-6, IL-8, TNF-α, IFN-γ, and MMP-9 were investigated by real-time PCR in the presence or absence of isorhamnetin." (PMID 33921231, 2021). "Tear volume, tear matrix metalloproteinase 9 (MMP‐9), perception of dry eye symptoms (frequency and severity), core temperature, and ocular surface temperature (OST) were measured at the end of each exposure." (PMID 31997577, 2020). "Increased ocular surface MMP-9 concentrations after refractive surgery (LASIK and PRK) are responsible for prolonged healing, dry eye symptoms, and haze." (PMID 31073413, 2019). "More interestingly, a recent study conducted on the effect of the MK2 inhibitor on a mice model of dry eye showed a suppression of cell apoptosis and a decrease of MMP3 and MMP9 in corneal epithelium." (PMID 30374345, 2018). "Trehalose application restored ocular surface integrity, suppressed inflammatory and proteolytic MMP-9 and HSP70 expression, and keratinization in mice with dry eye damaged by a desiccative model." (PMID 22355243, 2012). "Dry eye stimulated the expression of TNF-α and MMP-9, and activated the MAPK signaling pathway on the ocular surface in the dry eye mouse model." (PMID 21976951, 2011). "Tear osmolarity and MMP-9 levels are significantly increased in diabetic individuals exhibiting dry eye symptoms, even without severe retinopathy." (PMID 41303830, 2025).
dry eye (continued). "Also, notably, the previous literature showed elevated expressions of both MMP-2 and MMP-9 in dry eyes, and both MMP-2 and MMP-9 have been shown to preferentially degrade basement membrane components and are implicated in corneal epithelial wound healing." (PMID 38534403, 2024). "In the tears of keratoconjunctivitis sicca (KCS) patients, MMP-9 concentration and activity were increased, which lead to the destruction of cornea epithelial tight junctions, resulting in epithelial exfoliation with subsequence effects on the underlying wing cells." (PMID 38534403, 2024). "Overall, the correlation between MMP-9 and dry eye signs is not yet definitively established; therefore, further research should be conducted to verify this relationship." (PMID 35450324, 2022). "In addition to MMP-9, we also analyzed the level of the cytokines IL-1β and IL-8 after Femto-LASIK, which are also known to be elevated in dry eye." (PMID 35886858, 2022). "We performed a retrospective chart review for patients diagnosed with dry eye and investigated if associations existed amongst noninvasive tear breakup time (NIBUT); corneal staining scores; and MMP-9 grade, tear film osmolarity, and Schirmer's test I results." (PMID 35450324, 2022). "In relation to dry eye syndrome, a randomized, double-blind, clinical trial reported that oral supplementation with LUT, ZX, curcumin, and vitamin D3 for 8 weeks enhanced dry eye symptoms and attenuated eye inflammation by reducing MMP-9 levels in tears." (PMID 34677429, 2021). "MMP-9 immunoassay device is a rapid and precise tool that can measure MMP-9 in tear film with a sensitivity of 85%, a specificity of 94%, a negative predictive value of 73%, and a positive predictive value of 97% in diagnosing dry eye." (PMID 33845799, 2021). "Not all, but many TED patients complain of dry eye symptoms, and many molecules, including MMP-9, have been reported to be dysregulated in dry eye disease." (PMID 33498689, 2021). "Indeed, the ocular surface status in dry eye is affected by the pro-inflammatory mediators such as IL-1, IL-6, TGF-β, TNF-α, and MMP-9; neurotrophic factors such as NGF; and antigen-presenting cells." (PMID 32698387, 2020). "Active MMP-9, an important biomarker of dry eye, was found in untreated dry eye and vehicle treated dry eye, but was not present in control and UAMC-00050 treated samples." (PMID 33057006, 2020). "TNF-α and MMP-9, which participate in the mitogen-activated protein kinase (MAPK) signaling pathways in ocular surface epithelial cells, have previously been detected in the corneal epithelium and are upregulated in patients with dry eye." (PMID 26937680, 2016). "Increased MMP-2 and MMP-9 production has been observed in the tear fluid collected from patients with systemic dry eye and from those with nonsystemic dry eye." (PMID 26904272, 2016). "The expression of MMP9 and IL6 in dry eye patients may indicate that inflammatory mechanisms play a synergistic role in the development of the disease." (PMID 26221061, 2015). "MMP-9 is known as a nonspecific, late-phase, inflammatory marker in patients with dry eyes." (PMID 39797282, 2025). "Surprisingly, despite the changed OSDI score, we could not identify any change of the classical dry eye marker MMP-9." (PMID 35886858, 2022). "The evolution of the dry eye condition was assessed by histology, immunohistochemistry staining, scanning electron microscopy, and gene expression by using TaqMan gene assay technology (mucin-4 [MUC4], matrix metallopeptidase-9 [MMP9], tumor necrosis factor-α [TNF-α], and defensin β-2 [DEFB2)." (PMID 21245952, 2011). "Therefore, the present study aimed to evaluate the correlations between InflammaDry MMP-9, handheld I-PEN tear film osmolarity, and other ocular surface parameters, including Schirmer's test I, noninvasive tear break up time (NIBUT), and corneal staining scores in patients with dry eye." (PMID 35450324, 2022).
dry eye (continued). "In addition, this corticosteroid treatment could also be the reason behind the absence of classic dry eye signs, such as MMP-9 alteration and inflammatory cytokine elevations." (PMID 35886858, 2022). "For instance, the higher proportion of patients with SS-dry eye than non-SS had lower tear TSP-1 levels (55% vs. 29%, 95% confidence interval [CI] = 1.64 to 5.35, p < 0.05) and higher tear MMP-9 levels (65% vs. 24%, 95% CI = 4.46 to 19.81, p < 0.05)." (PMID 36675090, 2023). "The ratio between MMP-9 and its regulatory molecule, thrombospondin (TSP-1), which is expressed by the epithelial cells, has been proven to accurately distinguish between SS dry eye and non-SS dry eye, as a lower ratio signals a SS condition." (PMID 36675090, 2023). "Next, we divided each of the ocular surface parameters into two groups according to dry eye severity: the positive and negative corneal staining score groups; the <10 and ≥10 mm Schirmer test I groups; and the <5 and ≥5 s NIBUT groups and compared differences in MMP-9 grade between each group." (PMID 35450324, 2022).